RAD51 (RAD51 recombinase)
Diseases named in the same sentence as RAD51 in open-access papers (continued):
Sharing a sentence is not in itself a finding about the gene and the disease.
tumor (continued). "An increase in the number of DSBs and diminished HR capacity have been proven with tumor biopsy samples with RAD51 foci reduction and accumulation of DNA damage markers, such as γH2AX, pKAP1, and pRPA." (PMID 36253861, 2022). "The results showed that the RAD51 score of PARPi-resistant tumor samples was higher than that of PARPi-sensitive samples, and was negatively correlated with the clinical efficacy of PARPi." (PMID 36091750, 2022). "Combined targeting of Sam68 and Rad51 reduces the cell viability of BC stem-like cells and induces growth stabilization of tumor xenografts." (PMID 35217791, 2022). "Rad51 functions as a promising predictor for the identification of tumor eligible for the treatment of PARP inhibitor." (PMID 35875146, 2022). "In an exploratory biomarker analysis in TOPARP-B, a RAD51 foci score as a surrogate measure of HRR function was able to identify all BRCA1/2-altered and PALB-2 biallelic loss tumours in keeping with HRR loss of function." (PMID 36497408, 2022). "Increased basal Rad51 levels in transformed cells compared to those in normal MEF cells, shown in this study, are consistent with the current notion that Rad51 is often overexpressed in tumor cells, resulting in increased resistance to genotoxic therapy." (PMID 35408878, 2022). "Another study reported that the combination of adavosertib (AZD1775) and a Rad51 inhibitor (B02) significantly inhibited tumor growth in a xenograft mouse model carrying HPV-positive HNSCC, compared to HPV-negative HNSCC." (PMID 36338767, 2022). "Concerning fork restart, different groups have used tumor and normal cells to demonstrate that RAD51-mediated strand invasion facilitates reversed fork restart, although both RAD51-dependent and RAD51-independent fork restart occurs in most cases." (PMID 35969531, 2022). "RAD51 polymorphisms were also associated with the occurrence of a new primary tumor, while XRCC3 polymorphisms were associated with tumor differentiation grade." (PMID 36139526, 2022). "Tumor samples were immunohistochemically stained for RAD51, γH2AX, conjugated ubiquitin, and BRCA1 foci." (PMID 33670893, 2021). "A significant inverse correlation was found between the RAD51 score and the tumor response rate after chemotherapy." (PMID 34702316, 2021). "In a second study, RAD51 foci tumor staining was performed in seven patients before starting treatment with a PARPi." (PMID 33670893, 2021). "Three patients showed primary resistance to the PARPi and had RAD51 foci detectable in the tumor prior to treatment initiation and the other four patients with PARPi sensitivity had low RAD51 foci before PARPi started." (PMID 33670893, 2021). "Underscoring these vulnerabilities, it has been demonstrated that cytotoxicity generated in tumor cells with SSB repair inhibition and subsequent increase in DSB formation is exaggerated in tumors already deficient in HR (such as BRCA1/2 or RAD51 mutations)." (PMID 34746010, 2021). "The magnitude is a reflection, in part, 1) of the fact that RAD51 participates in the repair of 15–20% of induced DSBs in S and G2 cells and 2) the heterogeneity of tumor response." (PMID 33358698, 2021). "When comparing tumor samples and pair normal samples, 19 kinds of tumor subtypes had elevated RAD51 expression (19/33), and one kind had significantly decreased RAD51 expression (1/33)." (PMID 33952262, 2021). "Ascites-derived tumor cells from several other cancer types have also been used for studying RAD51 foci formation." (PMID 33670893, 2021). "Elevated levels of RAD51 expression also correlate with a grade of a tumor and poor disease prognosis." (PMID 34208492, 2021).
tumor (continued). "The reduction in EdU incorporation in MCF10A cells, coupled with the increased percent of cells in G1 following exposure to B02-iso, suggests that these non-tumor cells respond to RAD51 inhibition with a G1 arrest." (PMID 34208492, 2021). "Platinum-based chemotherapy was also shown to enhance HR as a DNA damage repair reaction, potentially upregulating BRCA1/2 and RAD51, so that an additional effect on tumor cell death of thiostrepton can be assumed." (PMID 33668819, 2021). "Our results are in agreement with several studies in which targeting either MRN complex or RAD51 sensitize tumor cells to radiation." (PMID 33632300, 2021). "The canine BRCA2 is a tumor suppressor gene which encodes the BRCA2 protein, involved in DNA repair through interaction with RAD51 recombinase." (PMID 34680380, 2021). "Subsequently, the tumor tissue is incubated for a few hours to allow accumulation of RAD51 protein at the breaks." (PMID 33670893, 2021). "Intra- and inter-tumor variation in the quality and quantity of RAD51 foci was observed among EC and OC specimens, as was aspecific RAD51 staining in some cases." (PMID 34203855, 2021). "They defined a RAD51 nuclear expression score (RAD51NES) using the average expression of RAD51 across all imaged tumor cells measured by qIHC." (PMID 33779077, 2021). "Quantification in formalin-fixed, paraffin-embedded (FFPE) tumour samples of the accumulation of the RAD51 protein in discrete, sub-nuclear structures termed “foci” by immunofluorescence (IF) techniques is one of the most advanced methods." (PMID 35008208, 2021). "Meanwhile, when the cells were treated with B02, a Rad51 inhibitor, silencing CD81 would not sensitize GBM cells to radiation, which further illustrates that Rad51 acts as an effector protein of CD81 in tumor radioresistance." (PMID 33919192, 2021). "As expected, restored BRCA1 expression has been correlated with the re-gained ability of the tumour to form RAD51 foci." (PMID 35008208, 2021). "Previous studies have also demonstrated that ATR inhibitors exhibit strong antitumor activity against HRR-deficient tumor models, such as those that are deficient in BRCA1/2, RAD51, or ATM-mutated." (PMID 34552099, 2021). "For example, knockdown of RBBP4 in GBM tumor cells results in suppression of the DNA-repair protein Rad51 due to disruption of the RBBP4/p300/CBP chromatin-modifying complex." (PMID 34086947, 2021). "NPC xenograft studies demonstrated that MGMT inhibition combined with CDDP treatment reduced tumor size and downregulated RAD51 expression and BRCA1 phosphorylation." (PMID 33397362, 2021). "In contrast to the RECAP test, the RAD51-FFPE test requires sufficient levels of endogenous DNA damage in tumor cells to allow evaluation of HR function by analyzing RAD51 protein accumulation at sites of DNA damage." (PMID 34203855, 2021). "We evaluated the performance of our published RECAP co-IF staining protocol for RAD51/GMN (with an anti-RAD51 antibody from GeneTex and an anti-GMN antibody from ProteinTech) in diagnostic FFPE tumor specimens." (PMID 34203855, 2021). "In a discovery cohort (n = 284), RAD51‐High tumours had shorter progression‐free and overall survival compared to RAD51‐Low cases in univariate and multivariate analyses." (PMID 33709473, 2021). "The RAD51-FFPE test was able to determine tumor HR status with high sensitivity and specificity, making it an attractive test to be applied as routine diagnostic tool in the near future." (PMID 34203855, 2021). "One XB type tumour (YOPC31) had mutations in the DNA damage pathway (RAD50, RAD51, BLM and BRD7), with the highest mutational burden (6.24 mutations/Mb), but the TIDE score of this tumour indicated lower responsiveness to anti-PD-1/PD-L1 therapy." (PMID 32235905, 2020).
tumor (continued). "As BRCA1, also BRCA2 plays an important role in tumor suppression and DNA repair process, probably for its direct interactions with Rad51 during homologous recombination in two different domains: the eight BRC repeat and DBD domain." (PMID 32438681, 2020). "All together, these results suggest that AKT inhibition in tumor cells leads to Rad51 down-regulation via ubiquitin-mediated proteasome pathway." (PMID 33266502, 2020). "The dynamics of DNA repair alter throughout tumour evolution and a functional RAD51 assay can be used as a dynamic readout of tumour HR status at the specific time for treatment decision-making." (PMID 32471999, 2020). "Patients whose tumor had a high expression of RAD51 showed significantly lower DSS after both 5 and 10 years compared to low RAD51 expression." (PMID 31963582, 2020). "As an alternative to DNA-based HRD tests, functional assays that assess the ability of replicating tumor cells to accumulate RAD51 protein at DNA DSBs were developed for use in breast, ovarian and endometrial cancer." (PMID 33003546, 2020). "Non-treated GIST T-1R cells exhibited a low level of γ-H2AX/Rad51 foci, whereas vast majority of tumor cells became γ-H2AX/Rad51-foci positive after Dox treatment." (PMID 33266502, 2020). "They proved that exosome-delivered RAD51 siRNA functionally inhibited RAD51 expression in tumor cells, induced the accumulation of cells in S and G2/M phases, and then caused massive reproductive cell death." (PMID 32489584, 2020). "We confirmed that RAD51 mRNA expression in tumor tissues was upregulated 2.5-fold when compared to paired adjacent non-tumor tissue." (PMID 31973027, 2020). "BRCA1 is a well-known tumor suppressor, but also has oncogenic roles with RAD51 through its DNA-repair function." (PMID 32572160, 2020). "We also observed that AKT signaling plays a regulatory role in the recruitment of Rad51 to DNA damage sites which was evidenced by a substantial decrease of number of residual Rad51 foci in Dox-treated tumor cells." (PMID 33266502, 2020). "Materials and Methods: The RAD51 expression was examined in 48 CRCs and paired adjacent non-tumor tissues." (PMID 31973027, 2020). "Elevated Rad51 levels were defined by the observation that at least 5% of tumor cells assessed demonstrated ≥ 5 Rad51 nuclear foci." (PMID 33216844, 2020). "The downregulation of RAD51, a key mediator of HRR, was observed in multiple cancer cell types induced by hypoxia, suggesting that the hypoxic tumor microenvironment can suppress the HRR pathway to cause genetic instability." (PMID 33628188, 2020). "Recently, two RAD51 paralogs have been clearly identified as tumor suppressors and the other three paralogs have been found to be mutated in some tumors." (PMID 31584931, 2019). "The increase of γH2AX and RAD51 foci is suggestive of the presence of stalled fork recovery sites and endogenous replication stress, both signs of the attempt by tumour cells to repair DNA lesions." (PMID 30357520, 2019). "The RAD51 immunostaining results in tumor tissue correlated with those of the western blot analysis, indicating that RAD51 is a key molecule in chemosensitization to cisplatin." (PMID 31640742, 2019). "The tumor suppressor BRCA2 played a major role in regulation of RAD51-catalyzed homologous recombination." (PMID 31506496, 2019). "RAD51 has recently received considerable attention due to its function in tumor progression and its decisive role in tumor resistance to chemotherapy." (PMID 31889908, 2019). "On the other hand, it was previously proposed that c-Met inhibition downregulated RAD51 and hence sensitized tumor cells to DNA damaging agents." (PMID 31857852, 2019). "Rad50, Rad51, Rad54b, Mre11a, Palb2, Brca1 and Bard1 all showed significantly higher expression in resistant tumours compared to responding tumours (p = 0.05, p < 0.001, p < 0.001, p < 0.001, p = 0.002, p < 0.001 and p = 0.012 respectively)." (PMID 31080552, 2019).
tumor (continued). "Our group and others have successfully identified tumor-specific promoters of two HR factors, RAD51 and RAD51C, which can be used for transcriptionally targeting tumor cells in vitro and in vivo." (PMID 29549248, 2018). "RAD51 foci formation had been proposed as a predictive biomarker of PARPi response; however, the assay required tumor biopsies either collected after patient exposure to DNA damaging agents or irradiated ex vivo." (PMID 30377213, 2018). "Several attempts to target RAD51-dependent repair have increased the sensitivity of tumor cells to radiotherapy, albeit to a variable extent." (PMID 30282933, 2018). "Out of 57 collected tumor samples, 48 samples contained sufficient tumor material to perform a RAD51-focus formation assay." (PMID 30550547, 2018). "The surgical pathologic stage, the percentage of viable tumor cells (or MPR), and RAD51 expression were associated with OS in both the univariate and multivariate analyses." (PMID 29673125, 2018). "The dynamics of RAD51 filament formation and stability is important for tumor suppression by maintaining genomic stability." (PMID 31435521, 2018). "We further investigated the functional status of HRR in FFPE tumors from PDX cohort‐1, scoring the percentage of RAD51‐positive tumor cells in S/G2‐phase of the cell cycle (geminin‐positive) following the protocol shown in Fig EV1B." (PMID 30377213, 2018). "Increased levels of Rad51 protein in tumor cells plays a central role in the HR-mediating repair of DSB." (PMID 30544713, 2018). "Fourteen out of 23 tumor samples showed low RAD51 score (≤ 10% cutoff), including all the eleven gPALB2 tumor samples." (PMID 30377213, 2018). "Our results show that RAD51 foci in PDX tumor samples correlated with PARPi response, while BRCA1 promoter hypermethylation, BRCA1 expression, BRCA1 foci, or HRR gene mutations did not fully correlate with PARPi response." (PMID 30377213, 2018). "We thus performed an exploratory polymerase chain reaction array of 84 key DNA repair genes and found that RAD51 has higher expression in CSCs than in bulk tumor cells in SUM149 cells." (PMID 28359295, 2017). "miR-107 and miR-222 sensitizes tumour cells to the PARP inhibitor olaparib by targeting the expression of RAD51 and, thus, impairing the HR pathway and repressing the DDR36." (PMID 29116111, 2017). "Geminin is known to be active in the late S-/G2-phase and was previously shown to be an excellent HR marker in combination with RAD51 staining in human tumour tissues." (PMID 29184099, 2017). "Early studies have shown that multiple immortalized, tumor cell lines and primary tumor samples overexpress Rad51." (PMID 28870216, 2017). "They identified Rad51 and Rad51D as key targets of miR-103/miR-107 that enabled the effects of the miRs in enhancing chemosensitivity of tumour cells." (PMID 27886180, 2016). "To accumulate further evidence for a potential role of RAD51 in tumor radioresistance, we constructed a TMA including 69 patients with resected GBM." (PMID 27495836, 2016). "Substantial crosstalk between the two pathways has recently been unravelled, in that key HR proteins such as the RAD51 recombinase and the tumour suppressors BRCA1 and BRCA2 also play important roles in ICL repair." (PMID 27037238, 2016). "In 29 patients with available tumor specimens, tumors with high expression of either LIN28 or OLIG2 or elevated level of Rad51 were significantly associated with poorer prognosis." (PMID 27074032, 2016). "The tumor growth curves indicated by the tumor volumes and the tumor weights both showed that A549/shRAD51 #1 cells were more sensitive to (−)-Guaiol, consolidating that RAD51 inhibition would greatly enhance the chemosensitivity of NSCLC cells to (−)-Guaiol." (PMID 27566579, 2016). "RAD51 is commonly recognized as an oncogenic driver in a band of tumors and is highly overexpressed in tumor tissues in patients with poor prognosis and low survival rate." (PMID 27566579, 2016).
tumor (continued). "To assess the mRNA levels of Rad51 in normal renal tissue and tumours, we performed RT-PCR experiments to measure the mRNA expression of Rad51 using the same tissue samples in western blot experiments." (PMID 27170370, 2016). "A subset of FA proteins includes the well‐characterised RAD51 recombinase, as well as the tumour suppressors BRCA1 and BRCA2, which are directly involved in the homologous recombination (HR) pathway of double‐strand break (DSB) repair." (PMID 27037238, 2016). "From a translational perspective, the tumor from which RAD51 G151D was identified turned out to be largely refractory to a range of therapeutic interventions including ionizing radiation (IR) and mitomycin C (MMC)." (PMID 27513445, 2016). "Cells with functional HR form RAD51 foci after DNA damage; there are attempts to establish ex vivo tumor HR testing using the analysis of induced RAD51 response." (PMID 27555886, 2016). "BRCA2 tumour-suppressor protein is well known for its role in DNA repair by homologous recombination (HR); assisting the loading of RAD51 recombinase at DNA double-strand breaks." (PMID 27628236, 2016). "Research showed that deletion of Rad51 gene would sensitize blastocytes of mouse embryos or tumor cells to genotoxic agents." (PMID 26752698, 2016). "We observed decreased expression levels of genes associated with DNA repair (MRE11, RAD51) and genes involved in cell cycle and chromosomal segregation (PLK1) after FOXM1 inhibition in both GBM tumor cells and stem cells." (PMID 27764801, 2016). "Inhibition of c-ABL by imatinib resulted in decreased expression of RAD51 in various tumor cell lines and, thus, in their reduced clonogenic survival after irradiation with up to 6 Gy." (PMID 26784176, 2016). "Studies from other researchers have confirmed that high-level expression of RAD51 has been shown to be related with median survival time, tumor differentiation, clinical stage, squamous pathology and lymphatic metastasis." (PMID 27566579, 2016). "The expression of Rad51 is tightly controlled in normal human cells; nevertheless, the majority of human tumor cells, including those of the breast, prostate, pancreas, lung, and cervix, overexpress Rad51." (PMID 27525019, 2016). "We assessed the RAD51 response in human tumour cells transfected with CBLC siRNA, as well as the formation of γH2AX foci, a marker of histone H2AX phosphorylation that is associated with DNA DSB formation." (PMID 25883215, 2015). "The tumor suppressor functions of RAD51 paralogs have been attributed to their role in DSB repair by HR and DNA damage signaling." (PMID 26354865, 2015). "Several studies reported that RAD51 overexpression induced tumor resistance to ionizing radiation and anticancer drugs in vitro." (PMID 26046797, 2015). "Rad51 paralogs, known tumor suppressors, induce remodeling at the tips of Rad51-ssDNA filaments to form an open and flexible conformation that promotes homologous recombination." (PMID 26186187, 2015). "Increased RAD51 expression was found in invasive ductal breast cancer and the level of overexpression correlated directly with the histological grading of the tumor." (PMID 25539919, 2015). "RECQL5 regulates HR by targeting undesirable RAD51-ssDNA filament, and is important for tumour suppression in mice." (PMID 24792170, 2014). "To validate our cell line data, we proceeded to evaluate RAD51 expression by immunohistochemistry in an independent cohort of 235 were sporadic tumours." (PMID 24811120, 2014). "Both cell lines expressing the firefly luciferase gene were orthotopically implanted into mammary fat pads of immunocompetent mice to determine if RAD51 knockdown impacts on primary tumour growth and/or metastasis." (PMID 24811120, 2014). "Recent studies have highlighted that silenced rad-51 is correlated with increased radiosensitivity of tumor cells and targeting rad-51 will be a potential target for combined therapies in clinic." (PMID 25026294, 2014).